ARNILA (androgen receptor negatively regulated lncRNA)
Gene: Long non-coding RNA gene on chromosome 2 (25,369,136 to 25,376,895, reverse strand). Ensembl gene ENSG00000235072.
Diseases named in the same sentence as ARNILA in open-access papers:
ARNILA is named in the same sentence as 4 diseases in open-access papers, as found by Europe PMC text mining. Sharing a sentence is not in itself a finding about the gene and the disease. The quoted sentences say what the papers report.
breast carcinoma (3 papers, 2019 to 2022). "For example, the lncRNA ARNILA was confirmed to sponge miR‐204 and to enhance breast cancer cell invasion and metastasis in breast cancer." (PMID 32885590, 2020).
triple-negative breast carcinoma (3 papers, 2019 to 2023). An invasive breast carcinoma which is negative for expression of estrogen receptor (ER), progesterone receptor (PR), and human epidermal growth factor receptor 2 (HER2). "It has been reported that long non-coding RNA ARNILA functioned as a competing endogenous RNA (ceRNA) sponge preventing miR-204 from binding the 3’UTR of SOX4 mRNA, thereby promoting EMT, invasion and metastasis of triple-negative breast cancer." (PMID 30691465, 2019).
cancer (1 paper, 2024). A tumor composed of atypical neoplastic, often pleomorphic cells that invade other tissues. "Additionally, many lncRNAs such as PCGEM1, CTBP1-AS, PCAL7, HOTAIR, CRPC-Lnc#6, SOCS2-AS1, NXTAR and ARNILA associate with ARs in different cancers and modulate various aspects of tumorigenesis and carcinogenesis via diverse mechanisms." (PMID 39199690, 2024).
tumor (1 paper, 2021). "In TNBC, multiple lncRNAs had been identified to regulate EMT pathways and tumor invasion via interacting with various molecules, such as LINC01638, GAS5, UCA1, ARNILA, and NNT-AS1." (PMID 34873403, 2021).